IL33 (interleukin 33)
Diseases named in the same sentence as IL33 in open-access papers (continued):
Sharing a sentence is not in itself a finding about the gene and the disease.
gastric cancer (62 papers, 2012 to 2025). A primary or metastatic malignant neoplasm involving the stomach. "Chronic HP infection inhibits NK cell toxicity, induces a long-term NK cell-associated IFN-γ response, and increases the risk of gastric cancer or inhibits IL-33, thereby limiting the activation of ILC2s that can clear it." (PMID 39309440, 2024). "This study aimed to evaluate the association between of serum IL-33 (sIL-33) level in gastric cancer (GC) patients and progression-free survival (PFS)." (PMID 28402273, 2017). "It has been recently shown that IL-33-activated mast cells, together with tumor-associated macrophages, allow for the progression of tumor angiogenesis and are correlated with poor survival in gastric cancer patients." (PMID 38339273, 2024). "Therefore, IL-33 has clinical value as a potential diagnostic tool for tumor patients, especially for gastric cancer and non-small cell lung cancer." (PMID 37507682, 2023). "In addition, Mast cells can be activated by IL-33 and release macrophage-attracting factors to promote the accumulation of tumor-associated macrophages, then promote the progression of gastric cancer." (PMID 37310469, 2023). "High expression of IL-33, assessed by IHC staining, was associated with advanced stage clear-cell renal carcinoma and abnormally high amounts of serum IL-33 was detected in patients with hepatocellular carcinoma or gastric cancer." (PMID 30416507, 2018). "High expression of ILC2 has been detected in solid tumors such as breast, lung, prostate, and gastric cancer, as the IL-33 produced by them is the main activator of ILC2 and usually promotes tumor growth, angiogenesis, and metastasis." (PMID 38861004, 2025). "In early-stage gastric cancer, IL-33+ endothelial cell subsets contribute to the progression of advanced disease by upregulating adhesion molecules, enhancing angiogenesis, and facilitating mucosal infiltration." (PMID 41303611, 2025). "In gastric cancer, IL‐33 and ST2 expression are higher in both intestinal metaplasia and GC tissues than in control tissues." (PMID 40860436, 2025). "A synergistic partnership between IL-33/Il1rl1 and Wnt pathway through Bcl-xL drives gastric cancer stemness and metastasis." (PMID 40659660, 2025). "In gastric cancer, a unique endothelial cell subtype called Venes-1 is characterized by the expression of IL-33 and MADCAM1." (PMID 41303611, 2025). "Within CAFs, elevated expression of NORAD augments the release of IL-33 to gastric cancer cells, thereby stimulating their proliferative activity." (PMID 39717771, 2024). "Eissmann and colleagues discovered that IL33 activates MCs, leading to a signaling cascade that is dependent on MCs and macrophages, promoting the growth of gastric cancer." (PMID 39087378, 2024). "High serum IL-33 concentration is reported to be associated with a poor prognosis in gastric cancer patients, and in vitro experiments suggest that IL-33 confers chemo-resistance and increases invasiveness to gastric cancer cells." (PMID 38339273, 2024). "IL-33 also stimulated the migration and invasion of human gastric cancer cells, human lung cancer cells, and human esophageal cancer cells." (PMID 37629196, 2023). "Previous studies have shown that under the stimulation of IL33, activated Mast cells can activate macrophages, thereby promoting the development of gastric cancer." (PMID 37915566, 2023). "In the analysis of cancer type subgroups, it was found that the serum levels of IL-33 in the gastric cancer group and non-small cell lung cancer group were higher than those in the control group." (PMID 37507682, 2023). "The serum IL-33 level was higher in the gastric cancer group (SMD = 1.770, 95% CI = 0.904–2.637, p < 0.000)." (PMID 37507682, 2023). "Several studies have demonstrated that IL-6-, IL-8-, IL-10-, and IL-33 mediated pathways are involved in the invasion and metastasis of gastric cancer." (PMID 35368661, 2022).
gastric cancer (continued). "In gastric cancer, CAF-derived IL-33 enhances the migration and invasion of gastric cancer cells by inducing the epithelial–mesenchymal transition (EMT), and the secretion of IL-33 by CAFs is dependent on the activation of the TNFR2-NF-κB-IRF1 pathway." (PMID 35251045, 2022). "Mounting evidence highlights a key role for IL-33 signaling in driving the stepwise progression of gastric cancer pathogenesis." (PMID 35677533, 2022). "Interleukin-33 (IL-33) is an IL-1 family cytokine known to promote T-helper (Th) type 2 immune responses that are often deregulated in gastric cancer (GC)." (PMID 35677533, 2022). "For example, in gastric cancer, the interaction between activated fibroblasts and tumor cells mediated by IL-33 signaling promoted tumor metastasis." (PMID 36439880, 2022). "Gastric cancer AGS cell line proliferation was reduced after IL-33 exposure, while normal gastric GES-1 cell line proliferation was induced at the same experimental conditions." (PMID 34071419, 2021). "Recently, we illustrated that MC numbers are elevated in human gastric cancer specimens and that high expression of an IL33-MC activation gene signature predicts poor survival of intestinal-type gastric cancer in patients." (PMID 32719677, 2020). "TTP was found to be remarkably reduced in gastric cancer and inversely correlated with interleukin 33 (IL-33) expression." (PMID 32545247, 2020). "Conversely, adoptive transfer of ST2-proficient MC stimulated tumor growth in ST2-deficient gp130FF mice, demonstrating that IL33-ST2 signaling within MCs is part of the tumor promoting effect of IL33 in gastric cancer." (PMID 32719677, 2020). "Conversely, elevated TTP expression was shown to inhibit the proliferation, migration, and invasion of gastric cancer cells through suppression of IL-33, a tumor promoting cytokine." (PMID 32545247, 2020). "In recent years, growing studies have demonstrated the potential role of IL-33 in the diagnosis of breast, lung, and gastric cancer." (PMID 33014844, 2020). "In human gastric cancer cell lines, IL33 promoted epithelial-to-mesenchymal transition in vitro and xenograft tumor growth in an ST2-dependent manner." (PMID 32719677, 2020). "Mast cells activated by IL-33 produced by tumor epithelium can promote the growth of gastric cancers." (PMID 31597362, 2019). "Mast cells are activated by interleukin (IL)-33, an alarmin produced by the tumor epithelium in response to the inflammatory cytokine IL-11, which is required for the growth of gastric cancers in mice." (PMID 31227713, 2019). "Mast cells activated by tumor-derived IL-33 can promote gastric cancer growth by mobilizing macrophage." (PMID 31597362, 2019). "Our findings delineate an IL-33/mast cell/macrophage axis, which affords a clinical opportunity for the treatment of gastric cancer." (PMID 31227713, 2019). "Here, the authors show, using genetic mouse models, that in gastric cancer, mast cells at the periphery of the tumors are activated via cancer cell produced-IL33 and promote tumorigenesis by recruiting macrophages within the tumors." (PMID 31227713, 2019). "In gastric cancer cells, IL-33 promoted cancer migration and invasion through stimulating the secretion of MMP-3 and IL-6 via aberrant activation of ST2-ERK1/2 pathway." (PMID 30619376, 2018). "Still, additional studies on human gastric cancer tissue and in vivo experiments in mice are required to further assess the function of IL-33 for gastric cancer development and progression." (PMID 28119694, 2016). "Human gastric cancer cell lines stimulated with IL-33 showed a dose-dependent increase in cancer cell invasion and migration." (PMID 28119694, 2016). "More following evidences have proved that IL-31 and IL-33 play an important role in some cancers' formulation, like lung cancer, gastric cancer, and squamous cancer." (PMID 27340318, 2016).
gastric cancer (continued). "In this study, we report that TTP suppresses the expression of interleukin-33 (IL-33), a tumor-promoting inflammatory cytokine, and thereby inhibits the progression of gastric cancer (GC)." (PMID 27074834, 2016). "Although we show here that IL33 is decreased after chronic H pylori infection, it recently was reported that IL33 serum levels are increased during gastric cancer." (PMID 28210674, 2015). "IL-33, released by stromal and tumoral cells, has been identified as a crucial factor in the tumorigenesis of myeloproliferative neoplasms and solid tumors, including colorectal cancers, gastric cancer, and squamous cell carcinomas." (PMID 40659660, 2025). "Notably, ST2 (IL1RL1), the receptor of IL‐33, was highly expressed in both endothelial cells and tumor cells, and its expression increased gradually with the progression of gastric cancer." (PMID 40860436, 2025). "Such as IL‐33 can be used as an early predictor of the efficacy of cetuximab in the treatment of colorectal cancer and the reduction of the toxicity of platinum‐based chemotherapy drugs to gastric cancer cells." (PMID 40860436, 2025). "Examples include the high expression of LOC100506114 enhancing GDF10 secretion to promote oral squamous cell carcinoma metastasis, LINC00152 enhancing CXCL-11 secretion to promote liver cancer metastasis, and NORAD enhancing IL-33 secretion to promote gastric cancer metastasis." (PMID 39717771, 2024). "Our study illustrated that DLL3 in stomach cancer could induce IL-1β, IL-12, and IL-10 secretion of macrophages via up-regulating IL-33." (PMID 35382168, 2022). "Furthermore, IL-33 levels are elevated in a variety of cancers, including gastric cancer, colon cancer, and head and neck cancer." (PMID 36110250, 2022). "These four proteins, including DLL3, IL-33, LG3BP, and HSPA8, could be a new insight into and promising diagnostic or therapeutic targets of stomach cancer." (PMID 35382168, 2022). "However, the role and mechanism of IL-33 in the interaction between gastric cancer (GC) cells and CAFs need investigation." (PMID 34895039, 2021). "Considering these results, caspase-3 may act as a tumor suppressor in human gastric cancer, and the data obtained by our ex vivo experiments show that the effect of IL-33 on the induction of CASP3 supports the potential role of IL-33 as an antitumor factor." (PMID 34071419, 2021). "Indeed some studies suggest that IL33 expression is decreased in more advanced disease while serum levels of IL33 increased in patient with advanced gastric cancer." (PMID 32719677, 2020). "Therefore, tumor-derived IL-33 sustains a mast cell and macrophage-dependent signaling cascade that is amenable for the treatment of gastric cancer." (PMID 31227713, 2019). "Similarly, IL-33 protein levels were significantly lower in gastric cancer tissues than adjacent tissues." (PMID 30483263, 2018). "Similarly, higher decline extent of serum IL-33 level was a predictor of shorter progression-free survival after chemotherapy in gastric cancer patients." (PMID 29568370, 2018). "IL-33 also promoted gastric cancer cell metastasis through ST2-ERK1/2 pathway." (PMID 29568370, 2018). "By in vitro and in vivo experiments, IL-33 was also shown to be able to promote growth, invasion and migration of gastric cancer and colorectal cancer cells due to the autocrine secretion of several metalloproteases (MMP3, MMP9, MMP2), IL-6 and CXCR4 via the ST2-ERK1/2 pathway." (PMID 30416507, 2018). "In vitro studies indicate that in human gastric cancer cells, IL-33 signaling occurs through pERK." (PMID 28423364, 2017). "Interleukin-33 appears to exert a pro-tumorigenic function in gastric cancer." (PMID 28119694, 2016). "For instance, IL-33 levels are increased in the serum of lung and gastric cancer patients and correlate with disease stage, suggesting that IL-33 may be a negative prognostic marker for these types of cancer." (PMID 28119694, 2016).
gastric cancer (continued). "Another study showed that serum levels of IL-33 were significantly higher in patients with gastric cancer than healthy people, suggesting that serum IL-33 levels may have a closer correlation with gastric cancer than IL-18 levels." (PMID 27014647, 2015). "Our data showed that the mRNA expression levels of the transcription factors RORα and GATA3, the receptors T1/ST2 and IL-17RB, surface markers CRTH2, and type 2 cytokines IL-33, IL-5, and IL-4 were significantly increased in PBMCs from patients with gastric cancer compared to healthy controls." (PMID 24741632, 2014). "In fact, a recent study has reported elevated IL-33 levels in the serum of gastric cancer patients that correlated with several poor prognostic factors, including depth of invasion, distant metastasis, and advanced stage, but not with the classic tumor markers, CEA and CA 19–9." (PMID 23062310, 2012). "As such, the initial observation of increased, circulating IL-33 levels in gastric cancer patients may be related to the progression of the cancer." (PMID 23062310, 2012). "In gastric cancer, existing studies on IL‐33 have focused mainly on mouse GC models, human‐derived advanced GC cell lines, and clinical samples for in vivo simulation and ex vitro experiments." (PMID 40860436, 2025). "Utilizing mouse models, we identified an IL33-MC-macrophage axis promoting gastric cancer growth where either ST2-deficiency, lack of MCs or lack of macrophages all restricted gastric cancer growth in the preclinical gp130FF mouse model of inflammation-associated gastric cancer." (PMID 32719677, 2020). "However, such IL-33 activity may potentially promote the development of gastric cancer induced by H. pylori infection." (PMID 32151084, 2020). "This suggests that IL33 serum levels may be a potential biomarker for gastric cancer." (PMID 28210674, 2015). "Therefore, the inhibition of gastric IL33 in response to chronic H pylori infection may be a key event in gastric cancer progression by preventing induction of Th2 immunity, and skewing the local immune response to Th1/Th17." (PMID 28210674, 2015). "In immunocompetent mice, intraperitoneal administration of IL-33 could induce a celiac inflammatory environment, activate immunologic effector cells, and reverse the immunosuppressive tumor microenvironment, which effectively delayed tumor progression and PM of gastric cancer." (PMID 38238529, 2024). "IL-33 and its receptor suppression of tumorigenicity 2 (ST2) are considered as prognostic markers for poor outcomes in gastric cancer." (PMID 39311766, 2024). "IL-33 promotes the production of IL-6 and MMP-3 by the ERK1/2 signaling pathway and enhances tumor invasion and escape ability in human gastric cancer (GC) cell lines." (PMID 36291105, 2022). "Thus, while targeting IL-33 could represent a novel therapeutic approach to stop the progression of gastritis to cancer in the early phases of tumorigenesis, at this stage, we cannot exclude that IL-33 may have a role in antitumoral activity in the advanced stage of gastric cancer." (PMID 34071419, 2021). "Results showed that IL-33 was downregulated in the GC group vs. HC (0.53 ± 0.30; p < 0.001), while ST2 L was upregulated in gastric cancer patients (3.12 ± 2.30; p < 0.05)." (PMID 34071419, 2021). "Notably, in a xenograft gastric cancer model adopting NOD/SCID mice, this IL-33/IL-2-dependent activation of ICOS+ Tregs is shown to promote tumor growth and progression." (PMID 38339273, 2024). "For example, as a proinflammatory factor, IL33 was shown to promote the malignant progression of gastric cancer by activating the downstream ST2/MAPK/ERK1/2 signaling cascade, which turned out to be a valuable prognostic biomarker for gastric cancer patients." (PMID 35368661, 2022).
gastric cancer (continued). "A recent analysis of ST2 genetic deficiency in a GC mouse model highlighted the importance of IL33/ST2 signaling in activating mast cells, which secrete chemotactic cytokines leading to the accumulation of pro-tumorigenic macrophages that drive gastric cancer progression." (PMID 35677533, 2022). "Upregulation of IL-33 is correlated with poor prognosis in gastric cancer, non-small cell lung cancer, and hepatocellular carcinoma." (PMID 30691509, 2019). "In a few tumor tissues of gastric cancer, lung cancer and colorectal cancer, we have found that IL-33 is of low or negative expression, while of high expression in serum." (PMID 28402273, 2017). "In addition, IL33 could also inhibit platinum-induced apoptosis and promote cell invasion via the ST2/MAPK/JNK pathway, conferring resistance to gastric cancer chemotherapy." (PMID 35368661, 2022). "Therefore, IL33 gene expression levels were analyzed by quantitative (q)RT-PCR in human gastric tissues from H. pylori positive subjects exhibiting gastritis (HP), pre-neoplastic adjacent-to-cancer intestinal metaplasia (IM) and gastric cancer (GC) as well as disease-free normal controls (N)." (PMID 35677533, 2022). "Moreover, gene expressions of DLL3, IL-33, LG3BP (also LGASLS3BP), and HSPA8 were analysed in UCSC Xena Functional Genomics Explorer based on the TCGA data set from 415 primary tumor samples of stomach cancer and 35 normal tissues." (PMID 35382168, 2022). "In order to assess whether or not the IL-33 inhibitory effect on cell replication was specific to the AGS cell line, we repeated the experiments on a different gastric cancer cell line, NCI-N87." (PMID 34071419, 2021).